RUNX1 (RUNX family transcription factor 1)
Diseases named in the same sentence as RUNX1 in open-access papers (continued):
Sharing a sentence is not in itself a finding about the gene and the disease.
ovarian carcinoma (continued). "At the same time, it has been reported that RUNX1 is upregulated in human ovarian epithelial cancer (EOC) tissues and is related to the proliferation, migration, and invasion of EOC cells." (PMID 37760803, 2023). "It is strongly suggested that overexpressed RUNX1 regulate the abnormal proliferation of ovarian cancer cells through the EGFR-AKT-STAT3 axis and RUNX1 work as a potential target for ovarian cancer treatment." (PMID 38057816, 2023). "Meanwhile, RUNX1 can regulate the proliferation of ovarian cancer through the TGFβ signaling pathway." (PMID 37760803, 2023). "Ovarian cancer cells display a high level of RUNX1 expression, which activates the NF-κB pathway, leading to chemotherapy resistance." (PMID 38057816, 2023). "In ovarian cancer, the interaction of RUNX1 with cofactors such as CBFB (core-binding factor beta) and SMAD proteins has been reported." (PMID 37760803, 2023). "It further highlights the potential of RUNX1 in the treatment of ovarian cancer and proves the necessity of in-depth research on RUNX1." (PMID 37760803, 2023). "This work opens a new unexplored avenue to investigate the enigmatic function of RUNX1 in neoplastic disease and identifies a novel role for the RUNX1 gene in the genetic landscape of ovarian cancer." (PMID 38057816, 2023). "This indicates that RUNX1 is closely related to the occurrence and development of ovarian cancer, as well as proves the necessity of further in-depth study of RUNX1 in ovarian cancer." (PMID 37760803, 2023). "RUNX1 knockdown inhibits the physiological function of ovarian cancer cells and regulates apoptosis through the FOXO1-Bcl2 axis." (PMID 38057816, 2023). "According to previous reports, RUNX1 deletion combined with chemotherapy drugs (taxanes, paclitaxel, and platinum) would have a better effect on chemotherapy resistance in ovarian cancer." (PMID 37760803, 2023). "At the same time, RUNX1 is overexpressed in ovarian cancer cells, which activates the NF-κB pathway and leads to chemotherapy resistance." (PMID 37760803, 2023). "TCGA and Kaplan Meier plotter databases showed that RUNX1 was highly expressed in ovarian cancer and significantly affected the survival curve." (PMID 38057816, 2023). "In recent years, studies have reported the roles of RUNX1 in solid tumors, including the significantly increased expression of RUNX1 in ovarian cancer." (PMID 37760803, 2023). "While a variety of the RUNX1 gene alterations have been identified in epithelial ovarian cancer, the most common is amplification." (PMID 36430923, 2022). "This discovery provides another supporting evidence for RUNX1 to conceivably play a tumor suppressor role in ovarian cancers." (PMID 35867729, 2022). "While our Runx1 KO mouse model is associated with GCT development, genomic alterations of RUNX1 in human ovaries have been so far mostly associated with epithelial ovarian cancer (EOC)." (PMID 36430923, 2022). "The RNA-sequencing analysis further revealed differentially expressed genes in Runx1 KO ovaries, including genes involved in metaplasia, ovarian cancer, epithelial cell development, tight junctions, cell−cell adhesion, and the Wnt/beta-catenin pathway." (PMID 36430923, 2022). "Combining the results of the two databases, we found that the role of RUNX1 in ovarian cancer was detrimental." (PMID 35534796, 2022). "In ovarian cancer, in vitro studies showed that RUNX1 inhibition in cell lines promoted cisplatin-induced apoptosis." (PMID 35867729, 2022). "Poor survival in ovarian cancer patients is correlated with high RUNX1 expression levels, and depletion of RUNX1 in ovarian cancer cells elevates cisplatin sensitivity." (PMID 36429115, 2022). "In particular, genetic alterations of the RUNX1 gene, including the amplification and deep deletion, have been previously documented in 1.5% of ovarian cancers according to the public data from The Cancer Genome Atlas (TCGA)." (PMID 36430923, 2022).
ovarian carcinoma (continued). "Recent studies have shown that Runx1, acting as an oncogene, is also closely related to the genesis and formation of a variety of cancers, such as ovarian cancer, esophageal cancer and breast cancer." (PMID 33479208, 2021). "We found that the low expression of RUNX1 mRNA was significantly related to OS of the ovarian cancer patients." (PMID 32111227, 2020). "Some studies on ovarian carcinoma have suggested that RUNX1 contributes to cell proliferation, migration and invasion." (PMID 31370857, 2019). "In addition, circMUC16 can directly associate with ATG13, stabilize its expression, and then promote autophagy in epithelial ovarian cancer by regulating Beclin1, RUNX1, and ATG13." (PMID 38338839, 2024). "It was also found in our study that depletion of RUNX1 could significantly enhance the inhibitory effect of chemotherapy drugs on ovarian cancer cells." (PMID 37760803, 2023). "With the deepening of research, RUNX1 may become a potential biomarker for ovarian cancer patients or be identified as a potential target for clinical treatment and achieve better efficacy." (PMID 38057816, 2023). "Moreover, the transcription factor RUNX1 was discovered to restrain cisplatin-induced apoptosis in ovarian cancer cells." (PMID 37760803, 2023). "Therefore, this review summarizes the reported signaling pathways involved in regulating RUNX1, to provide some help for follow-up research on and even treatment of ovarian cancer." (PMID 37760803, 2023). "Taken together, the over-expression of RUNX1 in HGSOC suggest that RUNX1 may play an essential role in the progression of ovarian cancer and seriously affect the prognosis of ovarian cancer patients." (PMID 38057816, 2023). "RUNX1 is highly expressed in ovarian cancer, and its expression level is dependent on Smad3." (PMID 37760803, 2023). "Therefore, these two ovarian cancer cell lines were selected for constructing RUNX1 stable knockdown cell lines and subsequent experiments." (PMID 38057816, 2023). "In addition, RUNX1 knockdown can significantly increase the sensitivity to clinical drug therapy for ovarian cancer." (PMID 38057816, 2023). "In conclusion, the transcription factor RUNX1 plays an important role in multiple solid tumors and is highly expressed in ovarian cancer, in which it plays a key role, indicating that RUNX1 has the potential as a biomarker for the diagnosis and treatment of ovarian cancer." (PMID 37760803, 2023). "The VEGFA-VEGFR2 Signaling pathway was enriched in the RUNX1 knockdown ovarian cancer cells." (PMID 38057816, 2023). "Although mis-expression of RUNX1 is associated with ovarian cancer, a direct causal link of Runx1 to the cancer formation is lacking." (PMID 36430923, 2022). "However, they also suggest that RUNX1 plays a protective role in four other cancers, including breast, eye, lung, and ovarian cancers." (PMID 35534796, 2022). "Therefore, while RUNX1 seems to play a tumor-suppressor role in mouse granulosa cells in our model, it has a more prominent oncogenic role in human epithelial ovarian cancer." (PMID 36430923, 2022). "In addition, another study has found that RUNX1 suppressed the expression of the miR-17~92 cluster in ovarian cancer." (PMID 33937021, 2021). "Therefore, circMUC16 first promotes autophagy of ovarian cancer through Beclin1, Runx1 and ATG13, and then the progression of ovarian cancer." (PMID 34445958, 2021). "RUNX1-205 lacks exon 6 in comparison with RUNX1b due to alternative splicing and plays a key role in ovarian cancer; however, its function in human hematopoiesis is unclear, which might be the final blank field of human RUNX1 variants research." (PMID 32313936, 2020). "In epithelial ovarian cancer, RUNX1 is significantly overexpressed due to DNA hypomethylation, and could promote cancer progression." (PMID 32746865, 2020). "Inhibition of RUNX1 promotes cisplatin-induced apoptosis in ovarian cancer cells." (PMID 33282553, 2020).
ovarian carcinoma (continued). "In ovarian cancer, RUNX1 negatively regulates the expression of the miR-17-92 cluster, which leads to the upregulation of BCL2, the direct target of miR-17-92, resulting in significant inhibition of cisplatin-induced apoptosis, which may be associated with cisplatin resistance." (PMID 38430423, 2024). "Together, RUNX1 may play an essential regulatory role in ovarian cancer development." (PMID 38057816, 2023). "Therefore, it is crucial to further elucidate the mechanism of RUNX1 in ovarian cancer." (PMID 37760803, 2023). "Therefore, for ovarian cancer patients with poor prognosis and drug resistance, reducing or inhibiting RUNX1 gene expression in ovarian cancer combined with cisplatin therapy may have a significant therapeutic effect as a combination treatment strategy." (PMID 37760803, 2023). "Therefore, this article reviews the relationship between RUNX1 and the occurrence and development of ovarian cancer, as well as the closely regulated signaling pathways, to provide some inspiration and theoretical support for future research on RUNX1 in ovarian cancer and other diseases." (PMID 37760803, 2023). "Silencing of RUNX1 reduced EMT and increased apoptosis via the FOXO1-Bcl2 axis while MICAL2 silencing suppressed ovarian cancer proliferation and migration, promoting a MET." (PMID 41282576, 2026). "Among these, RUNX1 and MICAL2 have been shown to regulate survival, EMT programs, and proliferation in ovarian cancer, rescpectively." (PMID 41282576, 2026). "However, the role of RUNX1 in ovarian cancer remains unclear." (PMID 37760803, 2023). "However, the mechanism of RUNX1, especially in ovarian cancer, is still largely unknown." (PMID 37760803, 2023). "Meanwhile, RUNX1 knockdown significantly decreased the phosphorylation level of EGFR and AKT in ovarian cancer cells." (PMID 38057816, 2023). "Therefore, RUNX1 cannot directly regulate the activity of the BCL2 promoter, and the investigators found that RUNX1 can regulate BCL2 through the miR-17–92 cluster in ovarian cancer, which may be part of the mechanism via which RUNX1 regulates BCL2 to further regulate apoptosis." (PMID 37760803, 2023). "Two ovarian cancer cell lines (SKOV3, OVCAR3) were transfected with the constructed RUNX1 shRNA to establish stable RUNX1 knockdown cell line." (PMID 38057816, 2023). "Interesting, it has not been reported that the specific mechanism by which RUNX1 regulates ovarian cancer cell apoptosis through FOXO1." (PMID 38057816, 2023). "Taken together, RUNX1, as a very important STAT3 regulator, may act as a signal transduction factor through EGFR, which provides a theoretical basis for further understanding the roles of RUNX1 in ovarian cancer." (PMID 37760803, 2023). "Meanwhile, mesothelioma (MESO), ovarian cancer (OV), and STAD outcomes were found to have a negative correlation with RUNX1 expression." (PMID 35534796, 2022).
glioblastoma (25 papers, 2014 to 2025). The most malignant astrocytic tumor (WHO grade IV). "The expression of Runt-related transcription factor 1 (RUNX1) is significantly higher in the mesenchymal subtype of glioblastoma and is strongly linked to the mesenchymal subtype initiated through miRNA-mediated pathways." (PMID 36793341, 2022). "An association between RUNX1 and maintenance of glioblastoma malignancy was thus estimated to be present." (PMID 36085167, 2022). "TRPA1 and TRPV1 are modulated by ERK signalling and transcription factor Runx1/Aml1 isoforms, influencing glioblastoma stem cell (GSC) differentiation and survival." (PMID 40806720, 2025). "This suggests that multiple pathways from RUNX1 suppression to cell proliferation suppression exist within “glioblastoma cell lines” due to the multiple targets of RUNX." (PMID 36085167, 2022). "In conclusion, Zhou and colleagues investigated the underlying mechanisms of temozolomide tolerance and discovered the miR-128-3p/RUNX1 pathway as a novel target for temozolomide tolerance in glioblastoma." (PMID 36793341, 2022). "They confirmed the oncogenic involvement of RUNX1 in glioblastoma cells and discovered miR-128-3p as a potent inhibitor of RUNX1." (PMID 36793341, 2022). "Taken together, RUNX1 was suggested to represent a crucial component in the maintenance of glioblastoma malignancy." (PMID 36085167, 2022). "It has also been observed that the downregulation of RUNX1 improves temozolomide sensitivity and suppresses glioblastoma growth." (PMID 36793341, 2022). "For example, in a patient with glioblastoma, tumor-normal match pair WES identified a germline variant RUNX1-M151L deemed likely pathogenic (ACMG guidelines) but not reported with tumor-only NGS (Caris Life Sciences) as it was not included in their panel." (PMID 32570879, 2020). "However, Chb-M’ inhibited cell proliferation in all four cell lines, suggesting that RUNX1 plays an important role in maintaining the malignant characteristics of glioblastoma." (PMID 36085167, 2022). "Transcription factors such as RUNX1 are believed to be involved in the malignancy of glioblastoma." (PMID 36085167, 2022). "However, RUNX1 silencing in U-87 MG human glioblastoma cells has been shown to inhibit tube formation in HUVECs." (PMID 36231060, 2022). "In addition, we evaluated the expression and survival of RUNX1 in the TCGA dataset for glioblastoma." (PMID 36085167, 2022). "Previous researchers reported that RUNX1 is involved in the aggressive nature of glioblastoma." (PMID 36793341, 2022). "Interestingly, in another study also using tube forming assays, treatment of human umbilical vein endothelial cells (HUVECs) with conditioned media prepared from RUNX1-silenced glioblastoma cells was able to have a similar suppressive effect on angiogenesis." (PMID 32154891, 2020). "Details of the effects of RUNX1 on the acquisition of malignancy in glioblastoma remain unclear." (PMID 36085167, 2022). "To further investigate the intonement of RUNX1 in regulating TMZ resistance of GBM, we first compared the level of RUNX1 in U87 and A172 glioblastoma cell lines to C8-DA astrocyte cells." (PMID 34895074, 2021). "In addition, it had been found that Runx1 could regulate the migration, invasion, and angiogenesis of human glioblastoma through the p38 MAPK pathway." (PMID 34169072, 2021). "Runt-Related Transcription Factor 1 (RUNX1) is highly expressed in the Mesenchymal (Mes) subtype of glioblastoma (GBM)." (PMID 31754093, 2019). "Elevated expression of RUNX1 has also been observed in glioblastoma (GBM) samples." (PMID 38430423, 2024). "Here, we show that RUNX1 downregulates p21 by enhancing expressions of BIRC5 and PIF1, conferring anti-apoptotic properties on glioblastoma." (PMID 36085167, 2022).
glioblastoma (continued). "In summary, we found that RUNX1 regulates the expression of BIRC5, which is involved in the induction of apoptosis in glioblastoma." (PMID 36085167, 2022). "However, the regulation of RUNX1 expression in glioblastoma remains unknown." (PMID 36793341, 2022). "In connection to previously reported glioblastoma mesenchymal signature transcription factors, SFRP2 increased and correlated with the expression of CEBPB, RUNX1, and FOSL2 in TCGA glioblastomas." (PMID 34021259, 2021). "Overall, our results provide new evidence regarding Runx1/Aml1 isoform overexpression and modulation in TRP channel expression during gliomagenesis, thus offering new directions for glioblastoma therapy." (PMID 34440820, 2021). "We hypothesised that RUNX1 regulates p21 and BIRC5 for some cells in glioblastoma and is involved in tumour growth." (PMID 36085167, 2022). "Similarly, the motifs CGR (breast invasive carcinoma), CACAAR (glioblastoma multiforme), ATGWTG (lung squamous cell carcinoma), CGWCCGAA (prostate adenocarcinoma) show exclusive affinity for YY2, RUNX1, ATF4 and ZBTB7B, respectively." (PMID 32015379, 2020). "Moreover, IL-1β induces RUNX1 expression through the MAPK signalling pathway and promotes migration, invasion, and angiogenesis in glioblastoma." (PMID 31592165, 2019). "Similarly, COL12A1 was upregulated with the growth of glioblastoma multiforme compared with normal brain, and when the proliferative potential of SKOV3 cells was reduced by knocking down the expression of RUNX1, COL12A1 expression also decreased." (PMID 24780490, 2014). "In glioblastoma (GBM), knocking down RUNX1 in U-87 MG cells inhibited angiogenesis, with p38 MAPK pathway inhibition by SB203580 denoting RUNX1's involvement in promoting vascular growth via the p38 MAPK signaling pathway." (PMID 39309442, 2024). "Furthermore, p21 expression was also upregulated in cells in which BIRC5, downstream of RUNX1, was K/D, suggesting that p21 was not directly regulated by RUNX1, but may be regulated via BIRC5 in glioblastoma." (PMID 36085167, 2022).
acute promyelocytic leukemia (24 papers, 2009 to 2025). An aggressive form of acute myeloid leukemia (AML), characterized by arrest of leukocyte differentiation at the promyelocyte stage, due to a specific chromosomal translocation t(15;17) in myeloid cells. "Assays have been developed for three phenotypes of particular clinical significance: NPM1, Core Bind Factor (CBF)-AML (referring to the fusions gene RUNX1::RUNX1T1 and CBFB::MYH11) and Acute Promyelocytic Leukemia (APL) (referring to the fusion gene PML::RARA)." (PMID 35892893, 2022). "The miR-181 cluster (miR-181a-3p, -5p and b-3p) showed a varied expression in their AML patients; in particular, it was high in the RUNX1/RUNX1T1-positive AML subtype, whereas only miR-181a-5p showed a steep increase in acute promyelocytic leukemia, where miR-181a-3p was usually downregulated." (PMID 33330086, 2020). "Importantly, PCR assays have been developed for three AML phenotypes: (i) acute promyelocytic leukemia (APL) (fusion gene PML::RARA); (ii) patients with NPM1 and CBF–AML (RUNX1::RUNX1T1 and CBFB::MYH11); and (iii) AML with fusion genes BCR::ABL1, KMT2::MLLT3, and DEK::NUP214." (PMID 37345204, 2023).